IGF1 (insulin like growth factor 1)
Diseases named in the same sentence as IGF1 in open-access papers (continued):
Sharing a sentence is not in itself a finding about the gene and the disease.
bronchopulmonary dysplasia (24 papers, 2012 to 2025). Bronchopulmonary dysplasia is a chronic respiratory disease that results from complications related to lung injury during the treatment of infant acute respiratory distress syndrome in low-birth-weight premature infants or from abnormal lung development in older infants. "Lower IGF1 levels are associated to critical patients who need erythrocyte transfusion, or respiratory support, or develop a bronchopulmonary dysplasia or a patent ductus arteriosus, i.e., situations all related to the genesis of ROP." (PMID 24523937, 2014). "Gestational age, bronchopulmonary dysplasia (BPD), and weight were significant confounders in the association between nutrient intake and IGF-1 levels." (PMID 32131447, 2020). "Both IGF1 and TNF-α have been implicated in various complications associated with prematurity, such as bronchopulmonary dysplasia and necrotizing enterocolitis, primarily through their roles in inflammation and growth regulation." (PMID 39194926, 2024). "In some congenital or genetic lung diseases such as bronchopulmonary dysplasia or cystic fibrosis, serum IGF-1 level was decreased in patients compared with the healthy population." (PMID 39220366, 2024). "Studies have also found that IGF-1 plays an important role in chronic lung diseases of premature infants and newborns, such as respiratory distress syndrome and bronchopulmonary dysplasia." (PMID 37705862, 2023). "Deregulation in immune responses has been associated with disturbances in IGF1 and IGF1R in typical neonatal pulmonary diseases, such as respiratory distress syndrome and bronchopulmonary dysplasia." (PMID 24391734, 2013). "In a phase‐2 trial involving extremely preterm infants (delivered < 28 weeks), systemic IGF‐1/IGFBP‐3 therapy led to a decrease in the occurrence of severe bronchopulmonary dysplasia and a non‐significant decrease in moderate‐to‐severe intraventricular hemorrhage." (PMID 40580544, 2025). "Interestingly, recent work demonstrated that postnatal treatment with recombinant human IGF-1 improves lung growth and structure in a model for bronchopulmonary dysplasia (BPD)." (PMID 34211985, 2021). "Increased expression of IGF-1 and IGF-1R from lung autopsy samples of babies who died from RDS and bronchopulmonary dysplasia suggests balanced IGF-1/IGF-1R being very important for lung development and maturation." (PMID 33917547, 2021). "Recently, intravenous supplementation with a complex of recombinant human (rh)IGF-1 and IGF binding protein-3 (rhIGF-1/rhIGFBP-3) to hospitalized preterm infants indicated benefits to decrease the incidence of bronchopulmonary dysplasia (BPD) and intraventricular hemorrhage (IVH)." (PMID 37404461, 2023). "This study aimed to determine whether postnatal treatment with recombinant human IGF-1 (rhIGF-1)/binding peptide 3 (BP3) ameliorates lung injury and prevents pulmonary hypertension (PH) in bronchopulmonary dysplasia (BPD) models." (PMID 37322452, 2023).
hyperandrogenism (24 papers, 2009 to 2025). Excessive secretion of androgens from the adrenal glands or gonads. "Components of cow milk, such as casein, whey proteins, hormones, and growth factors, can elevate androgen receptor activity by increasing insulin and IGF-1 levels, leading to hyperandrogenism and potentially exacerbating HS symptoms." (PMID 39768986, 2024). "Since IGF-1, acting in synergy with LH, stimulates androgen production by TC, omentin could be involved in the development of hyperandrogenism, particularly in obese subjects." (PMID 35701786, 2022). "Notably, IGF1 is also upregulated in women with PCOS, a condition often associated with hyperandrogenism." (PMID 31319382, 2019). "Furthermore, insulin also influences hyperandrogenism by inhibiting liver synthesis of SHBG2 and IGFBP-1, which binds IGF-1 IGF-1 is a growth factor with endocrine action." (PMID 27423183, 2016).
prostate tumor (24 papers, 2007 to 2024). "Also, experimental models in TRAMP mice have shown a higher weight of prostate tumors, accompanied by higher IGF-1 serum level with both zinc-deficient and zinc-enriched diet, in contrast to standard zinc diet, pointing to a U-shaped relationship between this micronutrient and PC." (PMID 30577563, 2018). "Microarray analysis of prostate tumors showed that IGF-1 was significantly down-regulated in HFD-fed Pten-knockout mice treated with antibiotics compared with HFD-fed Pten-knockout mice without antibiotics." (PMID 36900168, 2023). "Prostate tumor weight and growth were reduced by walnuts, accompanied by a decline in plasma IGF-1, resistin and LDL." (PMID 37237848, 2023). "Taken together, these data demonstrate the promotional role of Wnt/β-catenin activation in IGF1-induced prostate tumor cell growth." (PMID 36323713, 2022). "These lines of scientific evidence are consistent with previous in vitro studies and provide more relevant data to demonstrate the co-regulation of androgen, IGF1, and Wnt/β-catenin axes in prostate tumor development and growth." (PMID 35902588, 2022). "Activation of IGF1 axes further stabilizes cellular β-catenin and enhances its activity to directly promote prostate tumor development and growth." (PMID 36323713, 2022). "Elevating IGF1 signaling further cumulates Wnt/β-catenin pathways in transformed cells to promote prostate tumor development." (PMID 35902588, 2022). "In vitro and epidemiological studies have demonstrated that steroid hormones, leptin and insulin-like growth factor-1 (IGF-1), all of which are raised among obese individuals, increase prostatic tumour cell proliferation." (PMID 20976066, 2010). "Both IGF and FGF axes are known to be upregulated in prostate tumors and several groups have shown IGF-1 to be expressed in prostate tumor stroma." (PMID 20426842, 2010). "Short-chain fatty acids (SCFA) produced by GM can signal through IGF1 on prostate epithelial cells, activating MAPK and PI3K signaling pathways and stimulating prostate tumor growth." (PMID 38402385, 2024). "It has been shown that aberrant activation of IGF1 signaling can either directly or via activating AKT and GSK3β axes stabilize cellular β-catenin to augment its activity for prostate tumor growth." (PMID 35902588, 2022). "Similar to observations of AR and IGF-1 expression, levels of the anti-apoptotic protein BCL-2 and the ratio of BCL-2/BAX, a marker of prostate tumor proliferative potential, were higher in animals submitted to the CS protocol than in all other groups." (PMID 32321149, 2020). "Analyses of human prostate tumor specimens suggest that PI3K/AKT and MEK/ERK signaling pathways are frequently activated by IGF-1, ErbB2, and VEGF in prostate tumors, via the phosphorylation, subsequent activation of NF-κB, Bcl2 protein, and deactivation of p21 and Bad protein." (PMID 25003983, 2014).
schizophrenia (24 papers, 2012 to 2025). A major psychotic disorder characterized by abnormalities in the perception or expression of reality. "Some studies have reported an association between IGF-1 polymorphisms and serum IGF-1 levels in patients with schizophrenia." (PMID 33746806, 2021). "In 2004, Gunnell and Holly wrote a letter to the journal, Schizophrenia Research, proposing a hypothesis on how “deficient IGF-1 levels” would increase the susceptibility to SZ diagnosis." (PMID 40141202, 2025). "IGF-1 may be associated with the pathophysiology of schizophrenia, but this association remains controversial." (PMID 33746806, 2021). "Therefore, we hypothesized that IGF-1 would commonly be increased to compensate for the deficits in neuroplasticity and myelin formation that underlie schizophrenia and MDD10,32,44,46–48." (PMID 36670169, 2023). "There are data proving that the IGF-1 level is related to positive sensitivity to treatment in schizophrenia." (PMID 40416497, 2025). "The author has previously demonstrated that the IGF-1 level is related to the severity of immune-inflammatory disorders, morphometric disorders of the brain, and motor disorders (catatonia) in schizophrenia." (PMID 40416497, 2025). "Reduced IGF1 expression in the schizophrenia SEZ predicts decreased expression of neuronal progenitor and immature neuron marker mRNAs21." (PMID 38704390, 2024). "Other significant pathways have relevance to the regulation of neurogenesis and schizophrenia, including ‘IGF-1 Signalling’ and ‘VDR/RXR Activation’ (vitamin D receptor and retinoid X receptor pathways) (both p < 0.0001)." (PMID 38704390, 2024). "So far, several studies comparing peripheral IGF‐1 levels between schizophrenia patients and healthy controls have been conducted." (PMID 36448977, 2023). "Schizophrenia patients had significantly lower peripheral IGF‐1 levels compared to healthy controls (Hedges’ g −0.42, 95% CI from −0.79 to −0.04, Z = −2.73, p = .006), but between‐study heterogeneity was significant (Q = 20.26, p = .002, I2 = 70.38%)." (PMID 36448977, 2023). "Several studies, including meta-analyses, have shown that patients with MDD and schizophrenia have higher blood IGF-1 levels than controls." (PMID 36670169, 2023). "Schizophrenia patients under antipsychotic treatment seem to have lower peripheral IGF‐1 levels compared to healthy controls." (PMID 36448977, 2023). "We matched groups for BMI and excluded patients with DM and showed that serum IGF-1 levels were higher in patients with schizophrenia than in controls." (PMID 36670169, 2023). "Another study found a significant positive correlation between the magnitude of increase in IGF-1 levels and the magnitude of decrease in cortisol levels in 33 antipsychotic-naïve patients with schizophrenia during 3 months of antipsychotic treatment." (PMID 36670169, 2023). "In conclusion, schizophrenia patients under antipsychotic treatment seem to have lower peripheral IGF‐1 levels compared to healthy controls." (PMID 36448977, 2023). "Original clinical studies of any type that reported peripheral blood, serum or plasma IGF‐1 levels measured after fasting in schizophrenia patients and/or healthy control group were selected based on inclusion and exclusion criteria." (PMID 36448977, 2023). "Considering the variations in these findings, the blood IGF-1 levels in patients with schizophrenia are still controversial." (PMID 33746806, 2021). "The relationship between serum IGF-1 levels and psychopathology in patients with schizophrenia thus appears to be complicated." (PMID 33746806, 2021). "This study aimed to investigate the relationship between serum IGF-1 levels and psychiatric symptoms in patients with chronic schizophrenia." (PMID 33746806, 2021). "This is in agreement with previous studies that explored IGF-1 therapy to attenuate schizophrenia pathophysiology." (PMID 32431597, 2020).
schizophrenia (continued). "Antipsychotic treatment can increase serum IGF-1 levels in schizophrenia patients, and those patients with a greater increase showed a reduction in positive symptom scores to a higher extent." (PMID 32191705, 2020). "Specifically, plasma IGF-1 levels were decreased in antipsychotic-naive schizophrenia patients and were inversely correlated with positive symptom scores and hallucination subscores." (PMID 32191705, 2020). "Considering the obtained data, one can assume the role of genetically determined disorders of mitochondrial function, energy metabolism, and insulin signaling as well as immune changes related to impaired immunoregulatory functions of IGF-1 in the pathogenesis of some instances of schizophrenia." (PMID 40416497, 2025). "Furthermore, serum IGF-1 levels correlated positively with MDD symptom severity but negatively with schizophrenia symptom severity." (PMID 36670169, 2023). "Additionally, a pathway analysis identified three schizophrenia risk pathways, including EIF2-, IGF-1-, and 14-3-3-mediated signaling pathways." (PMID 37376599, 2023). "The subgroup in which peripheral IGF‐1 levels were measured in plasma was without any heterogeneity (I2 = 0.00%) in the meta‐analysis where schizophrenia patients were under antipsychotic treatment, but the combined effect size was nonsignificant (Hedges’ g 0.03, 95% CI from −0.02 to 0.08)." (PMID 36448977, 2023). "In schizophrenia (SZ), Down Syndrome, and bipolar disorder (BD), increased brain insulin resistance and reduced IGF-1 signaling drive allostatic load/overload, leading to physiological dysregulation and the presentation of more severe symptoms throughout the body." (PMID 36429060, 2022). "First, the sample size was small, and all patients with schizophrenia were in the chronic stage and had been receiving several antipsychotic drugs, which could have affected the serum IGF-1 levels." (PMID 33746806, 2021). "There are also indications that signaling pathways, including the IGF-1 pathway, may be involved in schizophrenia and other disorders treated with antipsychotic drugs." (PMID 33746806, 2021). "Therefore, it is plausible that synaptogenesis induced by IGF-1 underlies the association between serum IGF-1 levels and the PANSS scores of patients with schizophrenia." (PMID 33746806, 2021). "Previous studies have reported that IGF-1 levels are reduced in schizophrenia, and that the reduced IGF-1 levels may be involved in the pathogenesis, particularly in the negative symptoms, of schizophrenia." (PMID 33746806, 2021). "Researchers have shown that IGF-1 signaling plays a role in schizophrenia pathogenesis." (PMID 32191705, 2020). "Similarly, single nucleotide polymorphism and variable number tandem repeat polymorphism studies support the conclusion that the IGF‐1 gene is not involved in schizophrenia." (PMID 36448977, 2023). "We aimed to investigate if there is a significant difference in peripheral insulin‐like growth factor 1 (IGF‐1) levels between schizophrenia patients and healthy controls and to determine whether a difference exists before and after initiation of antipsychotics." (PMID 36448977, 2023). "Thus, we hypothesized that serum IGF-1 levels are affected by the DM status in patients with schizophrenia." (PMID 33746806, 2021). "Furthermore, IGF-1 levels were also decreased in an animal model of schizophrenia." (PMID 32191705, 2020). "Fifth, cortisol and IGF-1 levels were within normal ranges in all three groups with the exception of cortisol levels in five patients with MDD and two patients with schizophrenia." (PMID 36670169, 2023). "Although serum IGF-1 levels were higher in patients with MDD and schizophrenia than in the control group, the difference between MDD and schizophrenia patients was not significant." (PMID 36670169, 2023). "We investigated the differences in serum cortisol and IGF-1 levels among patients with MDD and schizophrenia and controls." (PMID 36670169, 2023).
schizophrenia (continued). "Age was significantly negatively correlated with serum IGF-1 levels in patients with MDD (R = − 0.54, p < 0.01) and schizophrenia (R = − 0.47, p < 0.01), and controls (R = − 0.55, p < 0.01)." (PMID 36670169, 2023). "Subsequently, we performed the analysis of covariance comparing serum cortisol and IGF-1 levels between patients with MDD and schizophrenia, using GAF, duration of illness, age, sex, and BMI as covariates." (PMID 36670169, 2023). "Serum IGF-1 levels were significantly higher in patients with MDD (p < 0.01) and schizophrenia (p = 0.01) than in controls." (PMID 36670169, 2023). "However, the precise relationship between IGF-1 and schizophrenia remains unknown." (PMID 33746806, 2021). "In the current study, imipramine or CP equivalent dose was not significantly correlated with serum cortisol or IGF-1 levels in patients with MDD or schizophrenia." (PMID 36670169, 2023). "We found a negative correlation between IGF-1 level and schizophrenia symptom severity, which is consistent with the results of several previous studies." (PMID 36670169, 2023). "In addition, the serum IGF-1 level of patients with MDD and schizophrenia was higher than that of controls." (PMID 36670169, 2023). "However, few studies have investigated the relationship between cortisol and IGF-1 in patients with MDD and schizophrenia, and the results have been inconsistent." (PMID 36670169, 2023). "The present study extended the observation period and recruited additional participants aiming to determine the differences in serum cortisol and IGF-1 levels between patients with MDD and schizophrenia, while controlling for confounding factors, such as fasting, comorbidities, age, sex, and BMI." (PMID 36670169, 2023). "The reason for the alteration in IGF-1 levels in patients with schizophrenia is not clear; however, it was not changed in the present study." (PMID 33746806, 2021). "However, no studies in humans, including patients with MDD and schizophrenia, have simultaneously examined peripheral and central cortisol and IGF-1 levels." (PMID 36670169, 2023). "There are indications that the insulin‐like growth factor 1 (IGF‐1) pathway may also be involved in the pathophysiology of schizophrenia but its precise role has not yet been determined." (PMID 36448977, 2023). "However, another study revealed elevated IGF-1 levels in patients with schizophrenia, but this result is not in accordance with the literature." (PMID 33746806, 2021). "Serum IGF-1 levels could not distinguish patients with schizophrenia and healthy controls." (PMID 33746806, 2021). "Serum cortisol and IGF-1 levels were not significantly correlated in patients with MDD (R = − 0.80, p = 0.37) or schizophrenia (R = − 0.17, p = 0.16), or controls (R = 0.16, p = 0.18)." (PMID 36670169, 2023). "However, to date, no studies have verified the differences in blood IGF-1 levels between patients with MDD and schizophrenia." (PMID 36670169, 2023). "In patients with schizophrenia, we found a significant positive correlation between serum cortisol levels and BPRS scores (R = 0.38, p < 0.01) and a significant negative correlation between serum IGF-1 levels and BPRS scores (R = − 0.50, P < 0.01)." (PMID 36670169, 2023).